ANKRD66 (ankyrin repeat domain 66)
Tractability: No criterion of Open Targets' tractability assessment is met for any kind of drug.
Gene: Protein-coding gene on chromosome 6 (46,746,933 to 46,759,506, forward strand). Ensembl gene ENSG00000230062.
Genetic constraint (gnomAD): Loss-of-function variants: 11 observed, 11.4 expected, observed/expected ratio (o/e) 0.96, 90% interval 0.61 to 1.58. The upper end of that interval is the gene's LOEUF score, 1.58, which puts it in group 6 of 6, group 1 being the genes least tolerant of losing a copy. Missense variants: 252 observed, 245.41 expected, observed/expected ratio (o/e) 1.03, 90% interval 0.93 to 1.14. Synonymous variants: 85 observed, 88.95 expected, observed/expected ratio (o/e) 0.96, 90% interval 0.8 to 1.14.
Homologues: Orthologues: chimpanzee ANKRD66 (98% identical), macaque ANKRD66 (96% identical), dog ANKRD66 (85% identical), pig ANKRD66 (82% identical), rabbit ANKRD66 (82% identical), rat Ankrd66 (79% identical), mouse Ankrd66 (76% identical), guinea pig ANKRD66 (68% identical), tropical clawed frog ANKRD66 (57% identical), zebrafish ANKRD66 (46% identical).
Diseases named in the same sentence as ANKRD66 in open-access papers:
ANKRD66 is named in the same sentence as 2 diseases in open-access papers, as found by Europe PMC text mining. Sharing a sentence is not in itself a finding about the gene and the disease. The quoted sentences say what the papers report.
tumor (2 papers, 2023 to 2025). "ANKRD66 is associated with enhanced cell proliferation in tumor cells, whereas PLA2G7 catalyzes phospholipid hydrolysis to produce arachidonic acid, participating in inflammatory signaling and lipid metabolism." (PMID 41246275, 2025).
cancer (1 paper, 2025). A tumor composed of atypical neoplastic, often pleomorphic cells that invade other tissues. "ANKRD66, an ankyrin repeat family member, may regulate cell proliferation via cytoskeletal dynamics, consistent with its proliferative role in cancer." (PMID 41246275, 2025).